CCND1 (cyclin D1)
Diseases named in the same sentence as CCND1 in open-access papers (continued):
Sharing a sentence is not in itself a finding about the gene and the disease.
tumor (continued). "In fact, incubation of RCC cells with thiazolidinedione decreased the protein levels of cyclin D1 and cdk4, and increased the levels of p27 which altogether led to G0/G1 arrest and massive tumor cell apoptosis." (PMID 19473483, 2009). "CCND1 expression has been increased in other tumour types by gene amplification or translocation, or controlled by alternative cell signalling pathways such as the sonic hedgehog pathway." (PMID 19293793, 2009). "Changes in expression of two in vivo identified genes, CCND1 and CDKN1A, encoding important cell cycle regulators were confirmed by IHC and immunoblotting on tumor cells." (PMID 19473496, 2009). "Recent evidence links nuclear retention of active cyclin D1/CDK4 complexes with genomic instability, providing a novel mechanism wherein cyclin D1 stabilization initiates tumor formation." (PMID 18764945, 2008). "Pin1 is a pivotal regulator of cyclin D1 expression, and disruption of the cyclin D1 gene in mice also suppresses the ability of the c-Neu transgene to induce tumor development in the mammary gland." (PMID 19077306, 2008). "Given the phenotypic outcome of accumulated nuclear cyclin D1/CDK4 complexes, further mechanistic investigation is required for development of novel therapeutic strategies to promote tumor cell death in cancers overexpressing cyclin D1." (PMID 18764945, 2008). "It has been demonstrated that carcinogenic compounds can induce cyclin D1 expression, which in turn promote tumor cell proliferation." (PMID 18197291, 2008). "Other studies have shown that tumours that express hormone receptors are also more likely to express CCND1." (PMID 21892296, 2008). "Associations of the cyclin D1 and EGFR pathway signatures with expression of CCND1 and EGFR, respectively, were also observed in two of the four tumor datasets." (PMID 18350153, 2008). "We observed that Ebp1's cytoplasmic expression also correlated strongly with the nuclear expression of Cyclin D1 and ErbB3 in both normal adjacent and tumor tissues." (PMID 19025630, 2008). "Increased tumour cell proliferation was observed in vivo, in line with the up-regulation of cyclin D1 and c-Myc in tumour cells 36 hours after induction of dominant negative E-cadherin." (PMID 18492263, 2008). "In fact, expression of the AR, Cyclin D1 and ErbB3 in normal adjacent tissue was found to be more informative than the corresponding tumor tissue in predicting PSA relapse in univariate models." (PMID 19025630, 2008). "According to our statistical analyses, Cyclin D1 expression was unrelated to all prognostic parameters as well as to histological subtype and tumor site." (PMID 18651966, 2008). "The bitransgenic tumours have a shorter latency than the c-ErbB2 tumours, but contain less phosphorylated Rb and less cyclin D1, which led us to examine some cell cycle inhibitors." (PMID 18700973, 2008). "By adding the molecular markers to the base model, we found that the two marker combinations in the tumor tissue were identified as independent predictors: CyclinD1+/ErbB3+ (HR = 0.44, P = 0.034) and Ebp1+/Cyclin D1- (HR = 4.79, P = 0.003)." (PMID 19025630, 2008). "Cyclin D1 is a downstream effector of β−catenin, promoting S-phase entry and tumor growth and is frequently upregulated in HCCs." (PMID 18382662, 2008). "Implicit to this data, if cyclin D1 is a driver oncogene, its overexpression in many cancers must be secondary to tumor-specific alterations that modify its subcellular location during the cell cycle." (PMID 18764945, 2008). "Immunoblot analysis revealed cyclin D1 in all samples with the bitransgenic tumours having a higher level of cyclin D1 than normal tissue, but the c-ErbB2 tumours containing more cyclin D1 than the bitransgenic tumours." (PMID 18700973, 2008). "Remarkably, cyclin D1-positive tumours displayed distinct localisation patterns, wherein tumours frequently exhibited predominately cytoplasmic cyclin D1." (PMID 17375037, 2007).
tumor (continued). "As in the initial cohort, tumours in the microarray with a high Gleason score maintained, cytoplasmic cyclin D1, but tended to be accompanied by higher nuclear cyclin D1." (PMID 17375037, 2007). "Specifically, cyclin D1-positive tumours were more likely to be derived from patients with lower preoperative PSA values, perhaps reflective of the established ability of cyclin D1 to modulate AR function." (PMID 17375037, 2007). "Cytoplasmic cyclin D1 staining was significantly increased in tumours compared to non-neoplastic tissue (p<0.05) and appeared to be predominant in Gleason 6 and 7 tumours." (PMID 17375037, 2007). "When the impact of cyclin D1 localisation on proliferation was examined, a statistically significant (P<0.01) difference was identified between predominately cytoplasmic cyclin D1 (4.33±0.63) and predominately nuclear cyclin D1 (12.5±2.77) tumours." (PMID 17375037, 2007). "Next, each gene’s expression in vivo, from 190 human tumor samples of various origins, was correlated to that of Cyclin D1 and the genes were ranked accordingly." (PMID 19079768, 2007). "The relevance of cyclin D1 status to the proliferative index was also considered, wherein tumours with predominantly cytoplasmic cyclin D1 exhibited the lowest proliferative index, even as compared to cyclin D1-negative tumours." (PMID 17375037, 2007). "Given the distinct patterns of localisation observed in the initial cohort of prostatectomy specimens, the prevalence of cyclin D1 staining patterns was examined as a function of tumour grade." (PMID 17375037, 2007). "The present data support a model wherein cyclin D1 accumulation and localisation are regulated as a function of tumour grade, and that differential cyclin D1 status significantly correlates with proliferation and PSA values." (PMID 17375037, 2007). "The opposite behaviours for cyclin D1 and cyclin E are in accordance with earlier observations showing that cyclin E overexpressing tumours are low in cyclin D1 and vice versa." (PMID 17254341, 2007). "Expression profiles showed some grade specificity, wherein nuclear cyclin D1 staining emerged almost exclusively in the higher grade tumours." (PMID 17375037, 2007). "Pharmacokinetic–pharmacodynamic relationships were established in the HCT116 human colon cancer xenograft model and showed reduced phosphorylation of RB and decreased expression of cyclin D1 in tumour tissue." (PMID 17179992, 2007). "The unique patterns of cyclin D1 in localised tumours prompted us to investigate cyclin D1 expression in metastatic tumours." (PMID 17375037, 2007). "Specifically, we showed a trend for increased p21Cip1 levels with tumour progression and that p21Cip1 is potentially elevated in tumours with high nuclear cyclin D1." (PMID 17375037, 2007). "Surprisingly, four distinct expression profiles were observed in these tumour sets, wherein a large fraction of cyclin D1-positive tumours showed cytoplasmic restriction." (PMID 17375037, 2007). "The level of bcl-xl and cyclin D1 was lower in STAT3 decoy ODN-treated tumor-bearing mice compared with that in vehicle control or scramble control (p < 0.05)." (PMID 17683579, 2007). "At the end of treatment, TUNEL and immunohistochemistry were used to examine the apoptosis and the expression levels of bcl-xl and cyclin D1 in tumor tissues." (PMID 17683579, 2007). "For example, elevated cyclin D1 with cytoplasmic cyclin D1 staining has been reported in many different tumour types, such as colorectal, pancreatic, lung, thyroid, and bladder." (PMID 17375037, 2007). "By contrast, nuclear cyclin D1 emerged in higher grade tumours (Gleason 8 and 9) and was also accompanied by high cytoplasmic cyclin D1 staining." (PMID 17375037, 2007). "In turn, the transactivation of β-catenin increases the transcription of genes that promote tumor cell growth, such as MYC, CCND1 (which encodes cyclin D) and JUN." (PMID 17764575, 2007).
tumor (continued). "Further analysis of tumor cell growth regulatory proteins indicated that receptor downregulation was associated with a decrease in the level of PKB/Akt, β-catenin, NF-κB, cyclin D1 and c-Myc." (PMID 16507132, 2006). "Similar results were found in AGS tumor cell line, so the cyclin D1 expression decreases of 34.56% to 4.11% and the cyclin E expression decreases of 72.01% to 2.01%." (PMID 16677386, 2006). "Cyclin D1 and pRb immunohistochemical data were correlated with tumor histological stage and grade, proliferative capacity (Ki-67 labeling index), and clinical parameters, in order to delineate their impact on prognosis." (PMID 16426443, 2006). "In the present study, only the survival of patients with cyclin D1 positive and advanced tumor stage (stage C and D) was significantly worse (P = 0.025)." (PMID 16426443, 2006). "This places severe limitations upon the extent to which a tumor cell can simply alter cyclin D1 levels as a means to achieve unrestrained growth properties." (PMID 16942622, 2006). "In many tumor types, the eukaryotic translation initiation factor eIP4e is dysregulated, and functions to induce cyclin D1 translational efficiency." (PMID 16863592, 2006). "In selected tumor types, cyclin D1 is overexpressed as a result of chromosomal translocation or amplification of the cyclin D1 (CCND1, PRAD) locus." (PMID 16863592, 2006). "These aberrations are often tissue specific, thus indicating that different tumor types favor differential avenues to disrupt the p16-cyclin D1-RB axis." (PMID 16863592, 2006). "The aim of this study was to assess the expression of cyclin D1 and pRb and to correlate them with tumor histological stage and grade, proliferative capacity (Ki-67 labeling index) and clinical parameters, in order to delineate their impact on prognosis." (PMID 16426443, 2006). "The β-catenin/TCF complex activates the transcription of Wnt target genes such as c-myc, cyclin D1 and human pituitary tumour transforming gene (hPTTG)." (PMID 16479254, 2006). "According to their effects on cell cycle progression, these regulators qualify as proto-oncogenes [cyclin D1, D2, E] or tumor supressors [p21, p27]." (PMID 16086840, 2005). "There was a statistically significant difference among cyclin D1 nuclear staining scores in terms of tumor size [p = 0.03]." (PMID 16086840, 2005). "In multivariate Cox analysis we compared the overall survival and the disease free survival according to clinical usual prognostic factors tumour size and nodal status and also to cyclin D1 and Ki 67 with the HIF-1α expression." (PMID 16035955, 2005). "Consistent with the cell proliferation and animal tumour growth data observed, cyclin D1 and PCNA index were significantly decreased by NS-398 both in vitro and in vivo." (PMID 14760389, 2004). "To further assess the inhibitory effects of NS-398 on cell proliferation and tumour growth, we measured cyclin D1 and PCNA levels using Western blot hybridisation and immunohistochemistry." (PMID 14760389, 2004). "With regard to cyclin D1, it is a well-known regulator of cell cycle and its overexpression plays an important role in tumour progression." (PMID 15292926, 2004). "High expression was found in 51% of tumours for cyclin E, in 33.7% for cyclin D1, and in 65% for p21." (PMID 15292923, 2004). "Over the past decade, the expression of CCND1 has emerged as being clearly disregulated in a variety of human neoplasms and having a major role in tumorigenesis." (PMID 15026807, 2004). "Survival in untreated patients with cyclin D1 high tumours was slightly better than for patients with cyclin D1 low/moderate tumours." (PMID 15138475, 2004). "The other main pattern, including 30% of the tumours, contained high p27 and cyclin E protein levels, but low levels, of cyclin D1 and D3." (PMID 12778072, 2003). "Our results suggest that up to 18-year old tumour samples can be used for immunohistochemical analysis of cyclin D1, D3, E, and p27." (PMID 12778072, 2003).
tumor (continued). "Earlier, we have shown that the cyclin D1 and E proteins were highly expressed in a large fraction of RCCs, and high cyclin D3 levels were observed in 16% of the tumours." (PMID 12778072, 2003). "Among the p27-positive tumours, cyclin D1 was the most frequently expressed cyclin either alone or in combination with cyclin E and/or cyclin D3." (PMID 12778072, 2003). "In the other tumours, cyclin E was highly expressed either alone or in combination with high cyclin D1 and/or D3 levels." (PMID 12778072, 2003). "Our data clearly motivate further studies of cyclin D1 in DCIS in order to validate the importance of this highly relevant tumour biological parameter as a potential prognostic marker." (PMID 14612904, 2003). "The only statistically significant link was between CCND1-unamplified-overexpressed tumours and oestrogen receptor positivity (P=0.0003)." (PMID 11870541, 2002). "Fourteen out of 16 (87.5%) PP tumours had an increase of CCND1, copy number between 2.70 and 13.18 and 12 out of 16 (75%) had polysomy 11, copy number between 2.70 and 5.88." (PMID 12237776, 2002). "It should be noted that this isolated tumour had a very low level of CCND1 overexpression (NCCND1=3.3)." (PMID 11870541, 2002). "The aim of this study was to determine if changes of the oncogenes c-myc and CCND1 in preinvasive tumours drive later progression." (PMID 12237776, 2002). "CCND1 has been identified as an oncogene, and is rearranged, amplified or overexpressed in a variety of tumours." (PMID 11870541, 2002). "Mice transgenic for cyclin D1 are prone to tumour development, the type of tumour being dependent on the enhancer sequence used to construct the cyclin D1 transgene." (PMID 11875707, 2002). "In total six out of 31 patients (19%) had amplification of CCND1 in their detrusor muscle invasive tumours, compared to two out of 31 (6.5%) patients with amplification of c-myc, N/S." (PMID 12237776, 2002). "Joint analysis of the CCND1 gene at both the mRNA and DNA levels showed that patients with a good outcome had CCND1-unamplified-overexpressed tumours while those with a poor outcome had CCND1-amplified tumours." (PMID 11870541, 2002). "As several studies have pointed to cooperation between the CCND1 and RB1 genes, and to their joint involvement in the proliferative capacity of tumour cells, we also sought a possible link between CCND1 DNA and/or mRNA status and RB1 mRNA underexpression." (PMID 11870541, 2002). "Six out of 30 (20%) tumours had amplification of CCND1, four of which were pT2 or above, the remaining two were pT1G3 and pTaG3." (PMID 12237776, 2002). "Patients with CCND1-altered tumours (n=47) were subdivided into those with CCND1-amplified tumours (n=15) and those with CCND1-unamplified-overexpressed tumours (n=32)." (PMID 11870541, 2002). "We developed a real-time quantitative RT–PCR assay based on TaqMan methodology to quantify CCND1 mRNA in homogeneous total RNA solutions obtained from tumour samples." (PMID 11870541, 2002). "The median value for cyclin D1 staining was significantly higher in Ta/T1 tumours (41%) compared with T2-T4 tumours (8%, P< 0.005) with 26% of muscle-invasive tumours demonstrating absent staining." (PMID 11161387, 2001). "The tumours that overexpressed cyclin D1 in more than 10% of neoplastic cells were considered positive." (PMID 10584879, 1999). "Of 28 cyclin D1-positive and 27 cyclin E-positive tumours, CDK4 was overexpressed in 12 (42.8%) tumours and CDK2 in seven (25.9%) tumours respectively." (PMID 10390005, 1999). "Staining signals of cyclin D1 and p21(waf1/cip1) were always nuclear but cyclin A was also expressed in the cytoplasm of the tumour cells." (PMID 10471053, 1999). "Nuclear immunostaining of cyclin D1 and cyclin E was observed in 28 (31.1%) and 27 tumours (30.0%) respectively." (PMID 10390005, 1999).
tumor (continued). "Using restriction fragment length polymorphism polymerase chain reaction and PCR-multiplex analysis, amplification of the cyclin D1 gene (CCNDI) was detected in 1/29 of the tumours demonstrating overexpression of cyclin D1 protein." (PMID 10584879, 1999). "Western analysis using a monoclonal antibody to cyclin D1 identified a 36 kDa protein in homogenates from seven tumours displaying cytoplasmic only and one tumour demonstrating both nuclear and cytoplasmic immunostaining." (PMID 10584879, 1999). "In a multivariate analysis, both cyclin D1 and CDK4 immunoreactivities (P < 0.01) and tumour stage (P < 0.001) were recognized as independent risk factors." (PMID 10390005, 1999). "The mean (range) fractions of cyclin A, cyclin D1 and p21(waf1/cip1)-positive tumour cells were 2.2% (range 0–20%), 23.3% (range 0–90%) and 6.8% (range 0–70%) respectively." (PMID 10471053, 1999). "The prognosis of patients with cyclin D1-positive tumours was significantly poorer than that of the other patients (P < 0.01)." (PMID 9459151, 1998). "A significant relationship between cyclin D1 expression and tumour proliferative activity was also found (P = 0.000001)." (PMID 9155044, 1997). "In the corresponding tumours, 48% (n = 16) were normal, while altered expression was found for cyclin D1 in 33% (n = 11), pRb in 27% (n = 9) and both in 9% (n = 3) of cases." (PMID 9192978, 1997). "Cyclin D1 is a cell cycle regulator essential for G1 phase progression and is frequently overexpressed in several human tumour types as a consequence of gene amplification or chromosomal rearrangements." (PMID 9192983, 1997). "Tumours with (++) staining for cyclin D1 recurred much more rapidly than (-) and/or (+) staining tumours (P < 0.01 for - vs ++; P < 0.05 for + vs ++)." (PMID 9192983, 1997). "We assessed the differences of disease-free interval in superficial tumours and actuarial survival probability in invasive tumours according to the status of cyclin D1 expression." (PMID 9192983, 1997). "As the p16 protein is involved in a cell cycle regulatory pathway consisting of at least pRb, cdk4 and cyclin D1, the tumours were also screened for amplifications of the last two genes." (PMID 8611425, 1996). "These tumours and 17 additional tumours with a normal gene copy number showed overexpression of cyclin D1 (25/53, 47%), as assessed by immunostaining using a monoclonal antibody." (PMID 8562333, 1996). "After affinity purification, the antiserum specifically detected overexpression of cyclin D1 in formalin-fixed, paraffin-embedded tumour material also." (PMID 8611372, 1996). "We did not encounter significant variability of staining within individual tumours with overexpression of cyclin D1." (PMID 8611372, 1996). "Overexpression of cyclin D1 is frequently found in various types of human tumours and results from clonal rearrangement and/or amplification involving chromosomal region 11q13." (PMID 8611372, 1996). "In parallel, we had also tested our tumour DNAs for amplification of CCND1, ERBB-2 and MYC, which made it possible to test for correlations with 20q13 or MDM2 amplifications." (PMID 8980401, 1996). "The well-established tumor-suppressing miRNA located within this small genomic region, miR-193a-3p, was downregulated in both bone metastasis and primary PCa cases, leading to overexpression of cyclin D1 and uPA to promote cancer cell migration and invasion." (PMID 41681875, 2026). "Additionally, SOX2 promotes tumor cell proliferation and survival by upregulating cyclin D1 and activating the Wnt/β-catenin pathway, contributing to aggressive tumor behavior in NSCLC." (PMID 41268614, 2026). "We identified potential oncogenes, including Igf2, Hras, Fgf3, Fgf4, and Ccnd1 in this amplicon that could promote tumor growth in mBT0309." (PMID 41568176, 2026). "This strategy decreased tumor size and the levels of cyclin D1 and VEGF." (PMID 41301028, 2025).